CLDN10 (claudin 10)
Diseases named in the same sentence as CLDN10 in open-access papers (continued):
Sharing a sentence is not in itself a finding about the gene and the disease.
endometriosis (1 paper, 2022). The growth of functional endometrial tissue in anatomic sites outside the uterine body. "A positive immunoreactivity of claudin-10 could also be identified in nearly all the endometriotic epithelial cells as well as in nearly all the endometriotic lesions of the three endometriotic entities: ovarian, peritoneal, and deep-infiltrating endometriosis." (PMID 36428908, 2022). "The quantification of claudin-10 using the HScore demonstrated a high degree of similarity between the patients with and without endometriosis, as well as the proliferative and secretory phases." (PMID 36428908, 2022).
fibrosis (1 paper, 2019). the formation of excess fibrous connective tissue in an organ or tissue in a reparative or reactive process. "We further bridged the Atp8b1G308V/G308V mice-based hyperoxia fibrosis model and human IPF pathology by revealing that IPF lungs display aberrant arrangement of CCSP-positive club cells in hyperplastic bronchiolar epithelium as well as increased claudin-10 expression in the lung." (PMID 30636723, 2019).
Hypermagnesemia (1 paper, 2020). An abnormally increased magnesium concentration in the blood. "Hypermagnesemia has been described in claudin 10 knockout mice; claudin 10 is expressed in the thick ascending limb of Henle loop that facilitates paracellular transport of Na+." (PMID 33282857, 2020).
kidney stone (1 paper, 2025). "Genes associated with the identified metabolites (e.g., CLDN10, OGFOD2, and GGT1) were found to have causal links to kidney stone formation." (PMID 40842671, 2025).
liver cancer (1 paper, 2020). An epithelial or non-epithelial malignant neoplasm that arises from the liver. "In liver cancer, CLDN10 overexpression may be correlated with cell proliferation and invasive abilities." (PMID 32045884, 2020).
liver cirrhosis (1 paper, 2017). "Notably, through literature reviews, we found that CLDN10, CDKN3, CRHBP and NEK2 were reported to be associated with HCC, and SPINK1 was associated with liver cirrhosis." (PMID 28036264, 2017).
mesothelioma (1 paper, 2023). A usually malignant and aggressive neoplasm of the mesothelium which is often associated with exposure to asbestos. "In conclusion, claudin-10 protein expression is higher in HGSC compared to mesothelioma, although the diagnostic power of this marker appear to be lesser than other claudin family members." (PMID 37067588, 2023). "Claudin-10 protein expression was found in 360/588 (61%) HGSC vs. 19/97 (20%) mesotheliomas (p < 0.001), and was higher in HGSC surgical specimens compared to effusions (p < 0.001)." (PMID 37067588, 2023). "In surgical specimens, claudin-10 performs better, as evidenced by expression in > 80% of tumors compared to 16% of mesotheliomas." (PMID 37067588, 2023). "Statistical analysis showed significantly higher claudin-10 expression in HGSC compared to mesothelioma (p < 0.001)." (PMID 37067588, 2023). "Beyond this, this suggests that claudin-10 is less robust than claudins 1, 3, 4 and 7 as a diagnostic marker of HGSC in the differential diagnosis from mesothelioma in serous effusions." (PMID 37067588, 2023). "Claudin-10 protein expression was found in 360/588 (61%) HGSC vs. 19/97 (20%) mesotheliomas." (PMID 37067588, 2023). "In conclusion, claudin-10 is overexpressed in HGSC effusions and surgical specimens compared to mesothelioma, though with lesser sensitivity and specificity as diagnostic marker compared to other claudin family members, particularly in effusion specimens." (PMID 37067588, 2023). "Our data consequently do not support replacement of claudin-4 by claudin-10 for differentiating HGSC from mesothelioma, nor its precedence over claudins 1, 3 or 7 as a second marker." (PMID 37067588, 2023).
ovarian endometriosis (1 paper, 2022). A non-neoplastic disorder characterized by the growth of endometrial tissue in the ovaries. "The different expressions of claudin-10 in the ectopic compared to the eutopic endometrium, especially in ovarian endometriosis, suggest that most of the changes occur after and not before implantation." (PMID 36428908, 2022).
peripheral nerve injury (1 paper, 2018). Injury to a peripheral nerve. "Western blots outcomes also suggested that protein expressions of claudin-10 and claudin-19 were down-regulated after peripheral nerve injury." (PMID 30425652, 2018).
renal carcinoma (1 paper, 2025). A carcinoma arising from the epithelium of the renal parenchyma or the renal pelvis. "In renal cancer, mutation of CLDN10 is rare and hypermethylation likely causes a loss of function of the B isoform." (PMID 40524239, 2025). "We identified Claudin 10 (CLDN10B isoform) to be epigenetically inactivated by DNA hypermethylation in renal cancer." (PMID 40524239, 2025). "In our study, we addressed this gap by investigating CLDN10 and showed that isoform B is epigenetically silenced in both post-transplant kidney tumors and conventional renal carcinomas." (PMID 40524239, 2025). "We identified the epigenetic silencing of the Claudin 10 gene isoform B (CLDN10B) through DNA hypermethylation in renal cancers, including clear cell (ccRCC), papillary (pRCC) and post-transplantation renal carcinoma (PT-ccRCC)." (PMID 40524239, 2025). "The methylation data of CLDN10 in renal cancer (ccRCC and pRCC) and PT-ccRCC led to our hypothesis of CLDN10B as a potential tumor suppressor in different types of renal cancer." (PMID 40524239, 2025).
tumor (24 papers, 2007 to 2026). "CLDN10, a member of the claudin family, maintains cell-cell adhesion, the loss of which has been considered to be the initial stage of tumor cell migration." (PMID 34721537, 2021). "Subsequently the association between CLDN10 and the level of immune cell infiltration in the tumor microenvironment was investigated using TIMER 2.0." (PMID 34721537, 2021). "Abnormal expression of CLDN10 may cause dysfunction of tight junctions, thereby affecting tumor progression, although this effect is complex." (PMID 34721537, 2021). "Generally speaking, abnormal expression of CLDN10 could affect the structure of tight junction, resulting in loss of cell adhesion, thereby promoting metastasis of tumor cells, enhancing tumor invasiveness and leading to poor prognosis." (PMID 34721537, 2021). "Regarding its expression levels, CLDN10 expression was significantly decreased with advanced tumor stage, but already present from stage g2 in ccRCC." (PMID 40524239, 2025). "Based on the TCGA database, the patients were divided into two groups (Tumor group and Normal group), of which 56 cases were normal controls, and high expressions were also observed on CLDN10, HMGA2, and LAMB3." (PMID 39205691, 2024). "Lung ex vivo imaging data indicated that CLDN10 overexpression also inhibited tumor cells' spontaneous lung metastasis." (PMID 35414767, 2022). "Based on these results, we identify that CLDN10 can not only predict the prognosis of ccRCC patients but also participate in the process of tumor growth and metastasis." (PMID 35414767, 2022). "By combining the CLDN10 expression data and clinical information of these 122 samples, we found that decreased CLDN10 expression was related to advanced tumor stage (T3/T4) and higher tumor grade (G4)." (PMID 35414767, 2022). "To verify the inhibitory effect of CLDN10 on ccRCC tumor growth and metastasis in vivo, we constructed a mouse orthotopic tumor growth model." (PMID 35414767, 2022). "The present study combined and analyzed the prognostic potential of CLDN6 and CLDN10 with the tumor immune microenvironment." (PMID 34249076, 2021). "Tumor purity was correlated with poor survival, confirming that CLDN10 expression was negatively correlated with tumor purity." (PMID 32045884, 2020). "Nevertheless, and clinically relevant, we and others observed loss of CLDN10 expression is associated with decreased patient survival and advanced tumor staging in ccRCC, irrespective of isoform levels." (PMID 40524239, 2025). "The higher expression of claudin-10 in surgical specimens obtained following neoadjuvant chemotherapy may suggest survival advantage for tumor cells expressing this protein." (PMID 37067588, 2023). "CLDN10 is a member of the tight junction protein claudin family, and abnormal CLDN10 expression may lead to tight junction dysfunction and thus affect tumor progression." (PMID 35875087, 2022). "In addition, after knocking down the expression of ATP5O based on the overexpression of CLDN10, the tumor growth and spontaneous lung metastasis rate was significantly restored." (PMID 35414767, 2022). "The expression of CLDN10 in T2 gastric cancer patients was associated with OS and PFS (OS p = 0.03; PFS p = 0.027), and the value of HR has a decreasing trend with increasing tumor development." (PMID 34721537, 2021). "Decreased expressions of claudin 1 and claudin 10 might lead to the compromised tight Junctions’ function and, thus, neoplasia progression was easy to comprehend." (PMID 23591077, 2013). "Decreased claudin 1 and claudin 10 expression may lead to the compromised tight Junctions’ function and the neoplasia progression." (PMID 23591077, 2013). "Similar results were obtained when analyzing the expression of CLDN10 and TMPRSS6 in LUAD tumor samples." (PMID 35178045, 2021). "In order to determine the impact of claudin-10 in the cross-talk between B-1 lymphocytes and the B16F10 tumor cells, we took advantage of small interfering RNA." (PMID 29145406, 2017).
tumor (continued). "An interesting observation is that expression of neither CLDN10 nor TMPRSS6 were associated with any immune population, suggesting that they are present in the primary tumor and not in the stromal compartment." (PMID 35178045, 2021). "On the basis of the PTC cohort from TCGA, a weak negative correlation was observed between CLDN10 expression and tumor purity (r=-0.133, P<0.05)." (PMID 32045884, 2020). "In addition, the tumor suppressor miR-486 and miR-367-3p have been shown to promote sorafenib sensitivity by inhibiting CITRON, claudin 10 (CLDN10) and androgen receptor (AR)." (PMID 31651347, 2019). "The silencing of claudin-10 expression in B-1 lymphocytes impairs the ability of the cells to induce the ERK phosphorylation in the B16F10 cells and to increase the aggressiveness of the tumor." (PMID 29145406, 2017). "CLDN10 showed a positive correlation with the immune cells, such as CD4+T cells and macrophages, and a negative correlation with tumor purity." (PMID 32045884, 2020).
cancer (14 papers, 2012 to 2025). A tumor composed of atypical neoplastic, often pleomorphic cells that invade other tissues. "The question of whether mutations of claudin-10 are also responsible for the cytoplasmic localization in cancer cells or ectopic endometrial cells remains to be determined." (PMID 36428908, 2022). "Abnormal expression of CLDN10 in GC may be associated with cancer progression." (PMID 35053454, 2022). "Regarding CLDN10 and cancer, studies reported it as an prognostic biomarker correlating with the immune microenvironment in ovarian cancer and its expression with overall survival of lung adenocarcinoma patients." (PMID 40524239, 2025). "In some cancer types, the relationship between CLDN10 overexpression and clinicopathological factors was associated with metastasis, cell proliferation, and infiltration capacity." (PMID 35053454, 2022). "Surprisingly, CLDN10 was overexpressed in cancer, but patients with high expression of CLDN10 showed good OS (HR = 0.73, logrank P = 1.6e-06), PFS (HR = 0.83, logrank P = 0.0067), and post progression survival (PPS, HR = 0.73, logrank P = 0.00029)." (PMID 34249076, 2021). "To predict the potential interactions between CLDN10 and other cancer-related proteins, we constructed a PPI network using a GeneMANIA database." (PMID 34721537, 2021). "In OB/OW subjects three genes were consistently overexpressed (TC2N, MIRLET7A2 and CLDN10) in the PP adipose tissue of men with cancer (EPCa or OCPCa), compared to BPH." (PMID 23009291, 2012). "To date, the antiapoptotic genes OLFM4, SIRT1, PIM-1, and DOCK3, the tumor suppressor PTEN, the cell proliferation and invasion genes CITRON and CLDN10, and FGF9 expressed by cancer-associated fibroblasts have been reported as potential targets for miR-486/miR-486-5p in malignant disease." (PMID 26895105, 2016). "Abnormal expression of CLDN10 may be involved in cancer progression." (PMID 32045884, 2020). "Of which, the top 20 differential expressed genes (DEGs) were mainly related to the progression of malignant tumors, including SYT12, CLDN10, COL9A3, SFRP1, MT1G, MTIH, etc.." (PMID 36253446, 2022). "Therefore, CLDN10 might serve different functions in different malignant tumors." (PMID 32045884, 2020).
genodermatosis (1 paper, 2024). "Given the potential for ED misdiagnosis in infancy, it is important to include the CLDN10 gene in a specific genodermatosis next-generation sequencing (NGS) panel to provide early diagnosis, accurate management, and genetic counseling." (PMID 38927623, 2024).
head and neck tumors (1 paper, 2021). "The mechanism of SLURP1 and CLDN10 in head and neck tumors deserves further study." (PMID 34631779, 2021).
infection (1 paper, 2023). The state of being infected such as from the introduction of a foreign agent such as serum, vaccine, antigenic substance or organism. "In the intestinal tract, the overexpression of Claudin 10 or the insufficient expression of Claudin 11 is usually induced by pathogen infection and considered as a sign of intestinal damage." (PMID 38137937, 2023).
CLDN10 also shares sentences with these, for which no sentence is quoted: hypohidrosis (4 papers); breast invasive carcinoma (3); adenocarcinoma (2); uterine corpus endometrial carcinoma (2); Azoospermia (1); biliary tract cancer (1); calculus (1); cholangiocarcinoma (1); colon adenocarcinoma (1); colon cancers (1); cutaneous melanoma (1); endometrial cancer (1); endometrioid adenocarcinoma (1); ependymoma (1); esophageal squamous cell carcinoma (1); fibroma (1); glioblastoma (1); head and neck squamous cell carcinoma (1); Hypercalciuria (1); Hypocalciuria (1); Hypokalemia (1); inflammatory bowel disease (1); kidney chromophobe (1); kidney disease (1); kidney tumors (1); laryngeal carcinoma (1); lung adenocarcinoma in situ (1); lung squamous cell carcinoma (1); migraine (1); myxoid liposarcoma (1).
A further 5 diseases each share a sentence with CLDN10 in 1 paper.